ALB (albumin)
Diseases named in the same sentence as ALB in open-access papers (continued):
Sharing a sentence is not in itself a finding about the gene and the disease.
tumor (continued). "Therefore, this study provides a simple and effective strategy for the development of albumin–cyanine dye complexes to enhance the water stability, biocompatibility, and tumor targeting specificity of many different polymethine cyanine dyes for future clinical use." (PMID 36614318, 2023). "In addition to GP60-mediated tumor distribution, there are reports that the secreted protein acidic and rich in cysteine (SPARC) may be attributed to the tumor distribution and uptake of albumin." (PMID 37049985, 2023). "In addition, many biomarkers have been proposed to determine the therapeutic effect of pembrolizumab treatment, such as tumor size, albumin, lymphocyte count, and lactate dehydrogenase level, however, none of these biomarkers accurately predicted the efficacy of pembrolizumab." (PMID 37202730, 2023). "Recent evidence suggests that a lower albumin level (a recognized marker of nutritional status), when combined with lymphocyte count in a Prognostic Nutritional Index, serves as a negative prognostic factor for patients with RCC, because it is associated with tumor progression and reduced survival." (PMID 38010650, 2023). "Moreover, patients with ALBI grade 2/3 had higher baseline total bilirubin (p < 0.001), protein induced by vitamin K absence or antagonist‐II (PIVKA‐II) (p = 0.006), and maximum tumor diameter (p < 0.001), and lower albumin (p < 0.001) than patients with ALBI grade 1." (PMID 36790032, 2023). "This could be solved by the addition of an albumin binder to the pyridine-based FAP-targeted ligands to extend their blood residence time as similar approaches have been exploited to Increase the tumor uptake of radiolabeled quinoline-based FAPI-04 derivatives." (PMID 36986548, 2023). "Low serum albumin level may predict short survival in tumor patients." (PMID 37735699, 2023). "Furthermore, we reported on the preparation of the novel multimodal boronated albumin-based theranostic agents, which could be accumulated in tumor cells." (PMID 36985644, 2023). "MoS2-CuO heteronanocomposites were then loaded with bovine serum albumin (BSA) and immunoadjuvant imiquimod (R837) on its surface to further form MoS2-CuO@BSA/R837 (MCBR) nanoplatforms, which had an excellent ability to eliminate the primary tumor and release tumor-associated antigens (TAAs)." (PMID 37627810, 2023). "Although the use of an albumin binder with lower affinity—such as p-(tolyl)butyric acid —could improve the tumor-to-background ratios of [177Lu]Lu-DOTA-IPB-NAPamide, the optimization of the unexpectedly high non-target uptake of the 177Lu-labeled derivative is part of future work." (PMID 37765089, 2023). "Several therapeutic nanoparticle (NPs) platforms, such as liposomes, polymers, and albumin NPs have already been utilized for cancer treatment to improve a drug’s solubility and stability, alter systemic exposure, promote tumor infiltrations, and enhance the uptakes of tumor cells." (PMID 36015206, 2022). "Therefore, by exploiting the biomimetic functions of serum albumin in this study, this bio-inspired NP system would possess prolonged blood circulation time, effective tumor-targeting capability, high accumulation rate, and deep tumor penetration capability are crucial properties in cancer therapy." (PMID 36134930, 2022). "In P2, the tumor nodule in segment 4 (T1a/T2a/T3a) harbored a subclonal KMT2C C983S mutation (cluster 13) and a subclonal KMT2C K1380M mutation (cluster 14) in T2a, whereas the tumor nodules in segments 5/6/7 (T1b/T2b/T3b) harbored a subclonal ALB L431fs mutation (cluster 7)." (PMID 35263170, 2022). "Furthermore, because the components of the CXI formula include albumin and neutrophil-to-lymphocyte ratio, the hepatic reserve function and the extent of tumor may affect the CXI." (PMID 35538112, 2022).
tumor (continued). "Albumin–PTX complexes might release the drug following the same pathway that the endogenous albumin is used as energy source by the tumor cell: endocytosis following albumin binding to receptors, which facilitates interaction of the drug with its therapeutic target." (PMID 36015347, 2022). "We examined serum albumin in relation to absolute monocyte count, absolute neutrophil count, NLR, and Systemic inflammation response index (SIRI) to determine if pretreatment serum albumin level is associated with these variables that have been linked to tumor inflammation status." (PMID 35393553, 2022). "In addition, compared to the pTNM model, the model constructed based on PNI, CRP-to-albumin ratio, percentage of preoperative weight loss, CA19–9, pTNM stage and tumor location could more accurately predict patient OS (C-index = 0.714 vs. 0.630, P < 0.001)." (PMID 36386538, 2022). "Thus, albumin exhibits passive tumor targeting due to EPR effect." (PMID 35203695, 2022). "This indicated that serum albumin level may be not only a surrogate of poor nutritional, but also driven by the aggressive tumor behavior and inflammatory status, which was correlated with shorter survival, treatment response, treatment-related toxicity and compliance." (PMID 35717275, 2022). "Uptake of albumin conjugates are presumably mediated by gp60 transcytosis pathway and subsequent specific binding to secreted protein acidic and rich in cysteine (SPARC) in tumor interstitium, and overexpression of SPARC is associated with enhanced tumor invasion, metastasis and thus poor prognosis." (PMID 35456631, 2022). "The prepared fluorescein-conjugated MIP was able to bind albumin, forming an albumin-rich protein corona, and to be passively accumulated in tumour tissue suggesting that this approach could be effective in the development of theranostic nanosystems for cancer therapy." (PMID 35225975, 2022). "In this study, we aimed to load Ap onto ChNPs and then coat them with albumin-folic acid to increase its bioavailability, solubility, and stability and may bind it to the target tumor cells by both albumin-binding protein and folate receptor (FR)-mediated endocytosis." (PMID 35745733, 2022). "Importantly, albumin can be inherently formulated in the hydrophobic anticancer drugs in its hydrophobic interiors, thereby improving pharmacokinetic (PK) profiles with an enhanced circulatory half-life of drugs for tumor-targeted delivery." (PMID 35456562, 2022). "Serum albumin has protective effects such as nutrition and anti-inflammatory, and fibrinogen can promote the invasion and metastasis of tumor cells through epithelial-mesenchymal transition and induce tumor blood vessel formation, thereby participating in tumor progression." (PMID 36686790, 2022). "Therefore, increased tumor accumulation of [131I]6 by structural modification such as conjugation with an albumin binder may make it possible to inhibit tumor growth." (PMID 34684688, 2021). "Moreover, nanoparticulate albumin DDS have been established in the form of nanoparticle albumin bound (nab)-paclitaxel, which uses nanoparticles as a carrier for paclitaxel and can thus achieve higher accumulation in tumor tissue as well as reduced systemic toxicity." (PMID 34680602, 2021). "Therefore, it is unclear whether the meso-Cl group would be required for the formation of albumin-complexes or the endocytosis of HMCDs into tumor cells." (PMID 34141613, 2021). "Furthermore, the introduction of a first immunocompromised version of the AlbuMus allows accurate anti-tumour investigations of an anti-EGFR x anti-CD3 bispecific albumin fusion in BRAF-mutated tumours non-respondent to standard anti-EGFR monoclonal therapies." (PMID 33686177, 2021).
tumor (continued). "Boron-albumin conjugates are promising anti-cancer therapeutics as they can be administered less frequently than alternative therapeutic agents and yet offer sufficient accumulation of the action component at the tumor site, which can improve the quality of life for cancer patients." (PMID 34770947, 2021). "However, neutron capture by this boron-containing albumin decreased the tumor cell survival." (PMID 34770947, 2021). "In addition, albumin is known to have immunomodulatory functions in tumor microenvironments." (PMID 34895201, 2021). "We found that male, multiple tumors, low albumin, high AST, high γ-GT, and high viral load were associated with positive AFP, suggesting that patients with positive AFP may tend to have poorer liver function and higher tumor aggressiveness." (PMID 34976804, 2021). "In addition, serum albumin binds to chemotherapeutic agents and delivers them to tumor tissues." (PMID 34895201, 2021). "Interestingly, HSA-d possesses a higher tumor distribution than HSA-m, so S-nitrosated HSA-d could enhance the EPR effect via an endogenous albumin transport (EAT) system." (PMID 34452170, 2021). "Since weight loss and serum albumin were the most relevant clinical symptoms/biochemical markers associated with survival in NEN patients, we further evaluated their relation to the molecular expression of ghrelin system components in tumor samples of 63 available patients." (PMID 35008278, 2021). "Besides, nano-albumin can be enriched in tumor sites by targeting to glycoprotein 60 (gp60)." (PMID 34600560, 2021). "However, in patients with early-stage NSCLC who underwent complete resection, postoperative albumin depletion might reflect a potential cancer recurrence before an apparent cancer recurrence is identified by tests such as computed tomography and tumor markers." (PMID 34473762, 2021). "Reduced ALB levels may furthermore reflect weakened antitumoral immunity, cellular phagocytic functions toward tumor cells, and antioxidant actions against the carcinogens, stimulated DNA repair and replication capacity of cancer cells, and decreased suppression of cell cycle and tumor progression." (PMID 33927759, 2021). "Hence, the endocytosis of albumin is the primary pathway for tumor accumulation of porphyrins." (PMID 33479459, 2021). "Thus, SPARC has been investigated as a potential therapeutic target, where the presence of SPARC in the tumour stroma could be used to deliver albumin-conjugated molecules into the tumour and TME." (PMID 34336679, 2021). "It is worth noting, that the utilization of albumin as a protein carrier to cancer cells has a great potential as seen in the case of aldoxorubicin which has emerged as a successful attempt at exploiting tumor accumulation of albumin as well as the acidic environment of solid tumors." (PMID 32079289, 2020). "Clinicopathological factors that serve as prognostic factors for UTUC include sex, age, tumor size, ureteral involvement, and body mass index, as well as laboratory markers such as the neutrophil-to-lymphocyte ratio, albumin, hemoglobin, and the prognostic nutritional index." (PMID 32859201, 2020). "In addition to patient, tumor, and treatment related characteristics, specific baseline frailty markers (Charlson comorbidity index, ECOG, patient reported weight loss, BMI, hemoglobin, creatinine, albumin) were recorded." (PMID 32306924, 2020). "Therefore, albumin-based nanocarriers could potentially overcome cancer drug resistance through bypassing drug efflux, enhancing drug uptake, and improving tumor accumulation." (PMID 35582218, 2020). "Furthermore, radioiodine cross-linking anti-EGFR (cetuximab) and bovine serum albumin (BSA) polycaprolactone (PCL) nanoparticles were also useful to induce tumor regression, which in turn enhanced the cytotoxicity on tumor cells and limited the adverse effects of chemical agents." (PMID 33321953, 2020).
tumor (continued). "Multivariate analysis identified pN stage, tumor differentiation grade, neutrophil count, and body mass index as independent prognostic factors for OS, and pN stage, tumor differentiation grade, neutrophil count, neutrophil-lymphocyte ratio, and serum albumin as prognostic factors for DFS." (PMID 33215031, 2020). "Nanoparticle delivery systems, such as liposomal, protein-based (e.g., albumin), and polymeric, have been shown to reduce systemic toxicity compared to free drug, as well as improved target site delivery, leading to increased drug concentration at the tumor site." (PMID 33134314, 2020). "Moreover, low albumin levels can impair the antioxidant actions against carcinogens, cellular and humoral immunity, and cellular phagocytic functions; stimulate the DNA replication in cancer cells; and resultantly enhance tumor growth rates." (PMID 33082783, 2020). "Recently, a mannosylated albumin delivery platform able to target both SPARC and CD206 was proposed in order to provide a more efficient way to target drug-resistant cancer cells and reprogram tumor-associated macrophages that over-express the mannose receptor." (PMID 31195727, 2019). "Consistent with their study, we demonstrated in the present study that the preoperative FP score was significantly correlated with age, tumor size, fibrinogen level, pre-albumin level and white blood cell count, and a high preoperative FP score could significantly predict unfavorable DFS and OS." (PMID 31772657, 2019). "Furthermore, albumin is found at high concentrations in tissue and tumor samples." (PMID 30609754, 2019). "It is noteworthy that albumin-stabilized AuNCs based nanoparticles could accumulate better in tumor tissues due to their higher size compared with AuNCs (≤10 nm), since blood vessels of tumor tissues are larger than 10 nm." (PMID 31295963, 2019). "One albumin was modified upon covalently binding doxorubicin through a peptide sensitive to cathepsin B to release the drug after particle internalization in the lysosomes, and the other one was modified with the peptide K237 to provide efficient targeting towards the tumor vasculature." (PMID 31195727, 2019). "Although both pretreatment CRP and ALB can be the independent prognostic factors of cancer patients, they are not perfect predictors because they can be easily influenced by some nontumor-related factors, such as diet, overhydration, and inflammation outside the tumor site." (PMID 29568406, 2018). "Thus, serum albumin level may reflect degree of oxidative stress and anti-tumor activity in patients with NAFLD." (PMID 29992975, 2018). "Due to its high water solubility and slow excretion, as well as its tight binding to serum albumin, EB has been widely used in biomedicine, including its use in estimating blood volume and vascular permeability, detecting lymph nodes, and localizing the tumor lesions." (PMID 29849513, 2018). "In addition, diet and other non-tumor-related factors can also affect the levels of serum albumin." (PMID 29685957, 2018). "In addition, our study extends the prognostic value of plasma BChE and albumin for all-cause mortality in an unselected treatment-naïve cancer patient cohort irrespective of tumor entity or stage." (PMID 29113384, 2017). "Finally, molecules other than serum albumin are also internalized via macropinocytosis, and uptake of these molecules might also contribute to tumor metabolism and growth." (PMID 29085336, 2017). "In addition, serum measurement of both CRP and albumin is less expensive than tumor markers." (PMID 28644836, 2017). "However, in addition to the immunological activity of FcRn involving IgG interactions and antigen presentation, our studies demonstrate that the levels of this receptor within the tumor cells themselves modulate cancerous growth by regulating albumin accumulation." (PMID 27974681, 2017).
tumor (continued). "Decreased serum BChE and albumin levels are associated with increased all-cause mortality in treatment-naïve cancer patients without a manifest malignant hepatic involvement irrespective of tumor entity or stage." (PMID 29113384, 2017). "Furthermore, COP-LMR was also associated with maximum tumor diameter (P < 0.001), WBC count (P < 0.001), hemoglobin (Hb) (P < 0.001), albumin (P < 0.001), alkaline phosphatase (ALP) (P = 0.005), D-dimer (P = 0.008), fibrinogen (P < 0.001) and survival period (P < 0.001)." (PMID 29069863, 2017). "The data clearly show that plasma levels of BChE and albumin are powerful predictors for all-cause mortality in an unselected treatment-naïve cancer patient cohort without manifest hepatic involvement irrespective of tumor type or stage." (PMID 29113384, 2017). "This kind of lipid bilayer-supported albumin conjugate with surface PEGylation is expected to prolong the blood circulation that will aid the permeation of tumor capillaries and extravasation into tumor fenestrations via the enhanced permeation and retention (EPR) effect." (PMID 28122339, 2017). "In patients at BCLC stage 0, patients’ age and low albumin were independent risk factors for OS, indicating that none-tumor factors may act as the predominant risk factors that determine the long-term survival in these patients." (PMID 28095820, 2017). "Importantly, since SPARC binds albumin with a high affinity, high SPARC tumor levels could enhance the accumulation of albumin within the tumor tissue, and improve the response to nanoparticle albumin-bound (nab)-paclitaxel in a targeted way." (PMID 27421134, 2016). "Besides lean body mass waste, tumour-bearing animals also showed a significant change in other parameters that indicates the establishment of the cachectic state, such as fat mass, water content and serum albumin concentration." (PMID 27388367, 2016). "However, according to the univariate analysis, AEG patients with hemoglobin ≥120 g/L, albumin ≥40 g/L, pre-albumin ≥200 g/L, tumor size <5 cm, PNI ≥51, and well differentiation grade had longer OS (P < 0.05), and this was consistent with an earlier T stage, N stage, or TNM stage (P < 0.01)." (PMID 27809860, 2016). "Thus, SPARC may have additional therapeutic benefit by enhancing the delivery of other molecules transported by albumin to tumor tissues." (PMID 27776337, 2016). "Hence the selection criteria for study entry focussed on those with a good performance status, low tumour burden and a normal serum albumin (a reliable prognostic factor), so that they were able to receive standard chemotherapy subsequently on disease progression." (PMID 27724887, 2016). "Similarly, it is reasonable that there were significant differences among the three COP-NLR groups in variables such as maximum tumor diameter, WBC count, platelet count, neutrophil ratio, lymphocyte ratio, monocyte ratio, Hb, LDH, albumin, fibrinogen, D-dimer, NLR, and intraoperative blood loss." (PMID 25950176, 2015). "Albumin nanoparticles could serve as a rational tumor-targeted drug delivery system because such nanoparticles would be expected to accumulate in solid tumors via the enhanced permeability and retention (EPR) mechanism when the size range is regulated at around 100 nm." (PMID 26404356, 2015). "Similarly, the development of albumin nanoparticles containing thiosemicarbazones, such as Dp44mT, may enhance the delivery, anti-tumor targeting, selectivity and toxicological profile of this agent." (PMID 25848850, 2015). "So they claimed that the tumor accumulation of IgG or albumin may be better than others." (PMID 26284588, 2015). "We also detected 147 gene fusions in non-tumor liver tissues, many of which involved genes with extremely high expression values in liver tissues, such as ALB, HP, and TF, suggesting that detected fusion transcripts may also have originated from SVs harbored within minor sub-clonal liver cells." (PMID 25526364, 2014).